IGF1 (insulin like growth factor 1)
Diseases named in the same sentence as IGF1 in open-access papers (continued):
Sharing a sentence is not in itself a finding about the gene and the disease.
cancer (continued). "Accumulating data have indicated the role of IGF-1 signaling pathway in lung development and diseases such as congenital disorders, cancers, inflammation, and fibrosis." (PMID 30018981, 2018). "Recent researches redefine the previously recognized role of IGF-1 signaling in lung development and diseases, such as congenital disorders, cancers, inflammation, and fibrosis." (PMID 30018981, 2018). "The indirect mechanism of metformin in anti-cancer function is related to its ability to lower insulin and insulin-like growth factor 1 (IGF-1)." (PMID 27902459, 2017). "Overall, in most cancer treatments, achieving a therapeutic reduction in endocrine IGF1 levels appears to be immensely favored in halting tumor progression." (PMID 28223541, 2017). "Several studies have shown that PPARγ/TZDs decrease IGF-1 levels and, thus, reduce cancer growth in carcinomas such as the pancreas, colon, liver, and prostate." (PMID 28348577, 2017). ", calcium, bone morphogenetic proteins (BMPs), fibroblast growth factors (FGF), and insulin-like growth-factor-1 (IGF-1) are released, enabling cancer cell proliferation and survival." (PMID 28194227, 2017). "The insulin/IGF-1 signaling pathway plays an important role in cell proliferation, apoptosis, and cancer." (PMID 29250031, 2017). "Using our novel graph-based approach, we observed a decrease in the expression level of the tumor suppressor insulin-like growth factor 1 (IGF1), and this decrease was primarily driven by a large methylation change in 5 different types of cancer." (PMID 28178311, 2017). "Insulin-like growth factor-1 (IGF-1) is upregulated in several cancers including PCa, and exhibits mitogenic and anti-apoptotic effects." (PMID 28125044, 2017). "Our result that IGF-1 is reduced in NPC patients contradicts those of other studies showing that serum IGF-1 levels are elevated in cancer patients." (PMID 28143425, 2017). "IGF1 is known to stimulate the PI3K/AKT pathway as well as the RAS/MEK/ERK cascade in cancer cells, which will finally end up in enhanced cell growth and inhibition of apoptosis." (PMID 29281661, 2017). "It is therefore not surprising that epigenetic and transcriptional changes in IGF1 signaling can induce cancer development and progression." (PMID 28173837, 2017). "Here, we found mutated genes at the level of the receptor itself in 7% of cases: focal amplification of IGF1R (n=3) and of IGF1 (n=2); frameshift indels in the recessive cancer genes, IGF2R (n=2) and IGFBP5 (n=1)." (PMID 28643781, 2017). "In addition, it is well known that IGF-1 might be associated with an increased risk of cancer." (PMID 29197368, 2017). "IGF-1 released by TAB cells induces heterogeneous tumor subpopulations with cancer stem cell-like characteristics that are defined as CD20+, CD133+, or CD271+." (PMID 28928360, 2017). "In alignment with this, population studies have demonstrated that the IGF-1 signaling pathway plays a significant role in the development and progression of many cancer types." (PMID 28539118, 2017). "Several studies have reported a correlation between circulating levels of IGF-1 and IGFBP-1 in healthy people and the risk of cancer development." (PMID 28143425, 2017). "PTEN, a well-known tumor suppressor that is competitively regulated by GAS5 in the subpathway region, inhibits the cancer-related IGF-1/mTOR pathway." (PMID 28152521, 2017). "High levels of circulating IGF-1 and certain genetic polymorphisms of IGF-1 and IGFBP3 increase the risk of several common cancers." (PMID 28954393, 2017). "The upstream regulators of these functions were predicted to involve the growth factors TGFB1, EGF, HGF and IGF1, which have known roles in activating these cancer progression pathways." (PMID 27965461, 2017). "Circulating insulin and IGF-1 primarily converge with intrinsic cancer cell metabolic processes via binding to their cell surface receptors, specifically insulin receptor (IR) and IGF-1R." (PMID 28959684, 2017).
cancer (continued). "The most evident effect of MBIs in healthy persons, particularly yoga and sitting meditation, was an increase in post-intervention levels of the IGF-1 neuropeptide, an important biomarker related to cancer prevention and other clinical conditions." (PMID 28231775, 2017). "IGF‐1 is known to promote cancer development by inhibiting apoptosis and stimulating cell proliferation." (PMID 27734632, 2016). "A potential drawback to the development of IGF1 small molecule inhibitors in cancer therapy derives from the finding that the receptors for both IGF1 and insulin exhibit close sequence homology and identical ATP-binding clefts." (PMID 27655636, 2016). "Insulin-like growth factor (IGF)-1 and other members of the IGF-1 pathway have been associated with development, progression, and metastasis of several cancers." (PMID 26738606, 2016). "In other words, cancer and CVDs appear to express two extremes of a fundamental metabolic disbalance that is related to factors such as cholesterol and IGF-1 (insulin-like growth factor)." (PMID 27680091, 2016). "Consistent with this expectation, hyperglycemia has been noted as an adverse event in clinical studies with the anti-IGF1 monoclonal antibody figitumumab in cancer patients, including those with MM." (PMID 27655636, 2016). "The modulation of plasma insulin and IGF-1 levels by pharmaceutical interventions is a promising approach for cancer treatment." (PMID 26878387, 2016). "We have previously shown that upon IGF-1 stimulation, the receptor becomes SUMOylated and translocates into the nucleus of cancer cells to act as a transcription co-factor." (PMID 27275536, 2016). "Previous study showed that Ras-Raf-MAPK signal, which acts as downstream of insulin/IGF-1 signaling plays a role in the proliferation of various cancers." (PMID 26901856, 2016). "We demonstrated that this phosphorylation is necessary for the nuclear translocation of PKM2 protein and, subsequently, its binding with STAT5 under IGF stimulation, which is critical for IGF-1-stimulated cancer cell growth." (PMID 27340866, 2016). "In conclusion, we demonstrated that PKM2 expression is crucial for the IGF-1-dependent activation of cancer cell growth, and that AKT directly binds with PKM2 to phosphorylate it at Ser-202." (PMID 27340866, 2016). "Insulin is known to increase IGF-1 levels, which decreases cancer cell death and increases cancer cell growth." (PMID 26959117, 2016). "We cannot conclude that our findings will facilitate selection of patients for IGF1-targeted therapy, which was recently evaluated in several types of cancer." (PMID 27144430, 2016). "Data from several genetic animal models of longevity have shown that reduced function mutations in the IGF‐1 signaling pathway have low circulating IGF‐1 levels, reduced cancer incidence, and increased maximal lifespan." (PMID 26443692, 2016). "Collectively, our data demonstrate a molecular mechanism of IGF-1 signaling in the context of altered tumor metabolism and support a crucial function of PKM2 for promoting the growth of cancer cells with aberrantly activated IGF-1/PI3K/AKT signaling." (PMID 27340866, 2016). "Previous studies showed that MAPK signal, which acts as downstream of insulin and IGF-1 proliferative signaling, plays a role in the proliferation of various cancers, including breast, colon and prostate cancer." (PMID 26901856, 2016). "Numerous studies have demonstrated that dysfunction of the IGF1 signaling pathway results in various diseases, including cancer, metabolic disease, as well as neurodegenerative diseases." (PMID 27213344, 2016). "In contrast, silencing TRIB3 decreases the basal and IGF‐1‐induced accumulation of SQSTM1 in cancer cells." (PMID 27038142, 2016).
cancer (continued). "Previous studies have shown that insulin and IGF-1 have pro-proliferation effects in various cancer cells." (PMID 26901856, 2016). "Specifically, our analyses provide evidence of physical and functional links between frequent, cancer-specific, chromosomal rearrangements and the IGF1 signaling pathway, an important cell survival network." (PMID 27285981, 2016). "In this context, downregulation of IGF-1 is potentially beneficial in treating cancer by RCSC alone or in combination with a known anti-cancer drug." (PMID 27806706, 2016). "The insulin-like growth factor 1 (IGF1) signaling pathway mediates multiple cancer cell biological processes." (PMID 27213344, 2016). "IGF1R activation by IGF1 can induce cell proliferation, cell survival, transformation, metastasis and angiogenesis as well as inhibit apoptosis in different cancer cell lines." (PMID 27941682, 2016). "In carcinogenesis, growth factors, such as IGF1 and insulin, stimulate growth and progression of cancer." (PMID 27255182, 2016). "Klotho is an established tumor suppressor, epigenetically silenced in breast and other cancers since it inhibits signaling pathways, such as IGF-1, PI3K, WNT, and TGFβ." (PMID 26556877, 2016). "The insulin/insulin-like growth factor-1 (IGF-1) system has thereby emerged as a key regulator of cancer growth pathways." (PMID 26878387, 2016). "This is in contrast to the theory that high carotenoid concentrationsmay protect from cancer by decreasing circulating levels of IGF-1." (PMID 27313849, 2016). "Data from experimental and epidemiological studies indicate that insulin‐like growth factor (IGF)‐1 and its binding proteins play a role in the biology of aging and in the pathogenesis of several common cancers." (PMID 26443692, 2016). "The complexity of the IGF-1 signalling axis is clearly a roadblock in targeting this receptor in cancer therapy." (PMID 27472395, 2016). "A large body of preclinical data has indicated that inhibition of the insulin/IGF-1 system has a therapeutic benefit for cancer-bearing animals." (PMID 26878387, 2016). "This indicates a broad spectrum of possibilities for modulating the insulin/IGF-1 system in cancer treatment." (PMID 26878387, 2016). "The interplay between steroid hormones and the IGF1 axis is of major clinical relevance in specific types of cancer, in particular adult epithelial tumors with a strong endocrine background." (PMID 27446805, 2016). "It has been widely accepted that insulin or IGF-1 promotes the proliferation of various cancers by activating MAPK signalings." (PMID 26901856, 2016). "Another signaling cascade that nimbolide targets to decrease proliferation and enhance apoptosis of cancer cells is the Insulin-like Growth Factor I (IGF-1) pathway." (PMID 27027349, 2016). "This section provides an overview of evidence for the emerging role of IGF‐1 in the development of first primary cancers, with a focus on epidemiological studies as well as experimental studies investigating the underlying biological mechanisms." (PMID 27734632, 2016). "This phosphorylation was essential for the nuclear translocation of PKM2 protein, allowing it to promote cancer cell growth under IGF-1 stimulation." (PMID 27340866, 2016). "Insulin-like growth factor 1 (IGF-1) is a crucial signal in the tumor microenvironment that promotes cell growth and survival in many human cancers." (PMID 27340866, 2016). "Considering the significant role of IGF-1 in cell growth and survival, inhibiting TPA-promoted IGF-1 signaling appears to be a critical target for cancer prevention." (PMID 27509024, 2016). "Myofibroblasts are the predominant stromal cell type in most carcinomas and have been shown to take part in tumour proliferation by secreting a number of growth factors, including IGF-1, IGF-II and HGF." (PMID 26979829, 2016).
cancer (continued). "Higher IGF-1 levels facilitate the more rapid proliferation of early cancers to the stage at which they can be clinically detected." (PMID 25866791, 2015). "Another potential application of our finding comes from the pleiotropic role of IGF1 in many developmental and physiological or pathological processes related to aging, longevity, energy metabolism, brain functions, and cancer." (PMID 25789079, 2015). "New advances in the molecular basis of anti-IGF1R blocking antibodies reveal they are biased agonists and promote the binding of IGF1 to integrin β3 receptors in some cancer cells." (PMID 25699021, 2015). "This study sought to investigate the role of IGFBP-3 in the adhesion of cancer and vascular endothelial cells to the ECM and the underlying molecular mechanism, with a focus on IGF-1 dependency." (PMID 25945837, 2015). "Here we found that inhibition of mTOR by rapamycin reduced the basal or type I insulin-like growth factor (IGF-1)-stimulated adhesion of cancer cells." (PMID 25762619, 2015). "The present study investigates the cytosine-adenine (CA) repeat polymorphism in the P1 promoter region of the insulin-like growth factor-1 (IGF-1) gene among cervical precancerous and cancer patients and healthy control females." (PMID 25384883, 2015). "Analysis of data from The Cancer Genome Atlas (TCGA) using the cBIO portal across most cancer types shows genomic alterations in IGF ligands (IGF1, 2), receptors (IGF1R, IGF2R), binding proteins (IGFBP1–6), and IRSs (IRS1, 2, 4); this representing 18 genes." (PMID 25964777, 2015). "In summary, we have demonstrated that rapamycin inhibits the basal or IGF-1-stimulated adhesion of cancer cells." (PMID 25762619, 2015). "Collectively, these findings indicate that blockade of the IGF1R with cix induces IGF1 to bind to integrin β3, which in turn induces Src signaling that increases cancer cell growth." (PMID 25699021, 2015). "IGF-1 mediates cancer cell migration, invasion and angiogenesis and mediates its intracellular signal by activation of IGF1R-PI3K-Akt signaling pathway." (PMID 25629162, 2015). "The IGF receptors are expressed in a variety of cancers, and in vivo studies have demonstrated that cancer cells have a dependency for IGF1." (PMID 26107517, 2015). "Many cancer cell lines express insulin and/or IGF1 and/or hybrid receptors, and depend on insulin/IGF1 for in vitro growth." (PMID 26284118, 2015). "The circulating IGF-1 levels are closely associated with the risk of cancer, and the blockade of IGF-1R, using anti-IGF-R1 antibodies, IGF1R antisense, and inhibitory analogues of IGF-1 suppress tumor cell growth and angiogenesis." (PMID 25638159, 2015). "In particular, germline polymorphisms in IGF1, IGF1R, and IGFBP3 are associated with increased risk of breast, prostate, lung, and pancreatic cancers." (PMID 25964777, 2015). "For example, insulin or IGF-1 increased cell proliferation and reduced apoptosis in cancer cells, even at physiologically relevant concentrations." (PMID 25866823, 2015). "The production of PGE2 is reportedly upregulated in numerous cancer types and the circulating IGF-1 levels are relatively stable." (PMID 25638159, 2015). "The PI3K/Akt pathway is one of the important downstream pathways of the IGF-1 pathway, and numerous studies have confirmed its role in the apoptosis of cancer cells." (PMID 25759982, 2015). "IGF-1 is important for both the regulation of normal physiology and a number of pathological states, including cancer, and it has been shown to play roles in the promotion of cell proliferation and in the inhibition of apoptosis." (PMID 26670463, 2015). "An increased insulin or IGF-1 level, which presents in T2DM, obesity, and acromegaly, is strongly associated with increased cancer risk and mortality." (PMID 25866823, 2015). "Many epidemiological studies have suggested that insulin and IGF-1 play important roles in the regulation of cancer." (PMID 25866823, 2015).
cancer (continued). "Here we found that disruption of mTORC1 or mTORC2 by silencing raptor or rictor, respectively, inhibited the basal and IGF-1-stimulated adhesion of cancer cells." (PMID 25762619, 2015). "Over the last decade, there has been increasing interest in the studying of the genomic analysis of the IGF-1 gene for specific alterations involved in cancer formation and progression." (PMID 25743390, 2015). "Higher IGF-1 levels have been associated with lower incidence of cardiovascular disease (CVD) and cognitive dysfunction in the general population, but lower IGF-1 levels have been related to decreased incidence of several forms of cancer." (PMID 24618355, 2014). "Insulin-like growth factor-1 (IGF-1) signaling promotes cell growth and is used as a crucial proliferative marker in cancer cells." (PMID 24970012, 2014). "Coupled with its role in inhibiting the protein synthesis in cancer cells, controlling gluconeogenesis and glucose uptake and influencing insulin/ IGF-1 levels and signaling, makes it an attractive contender mediating the antitumor effects of CR." (PMID 25026276, 2014). "In contrast, our immunohistochemical findings correlate with most literature on the role of increased IGF1 in cancer progression." (PMID 24708576, 2014). "Activation of IGF1R which is essential for the initiation and progression of many cancers starts by ligand-initiated kinase activation with IGF1 or IGF2." (PMID 25344917, 2014). "Both insulin and IGF-1 induce proliferation and inhibit apoptosis in various cancer cell lines, including ovarian." (PMID 25026276, 2014). "IGF-1 signaling can contribute to each stage of cancer progression: malignant transformation, tumor growth, local invasion and distant metastases, and resistance to treatment." (PMID 25333772, 2014). "We first performed a wound-healing experiment in vitro and found that IGF-1-induced cancer cell motility (as assessed by wound healing) was suppressed by treatment with 200 μg/ml anthocyanin." (PMID 24666969, 2014). "From the dissection of hsa05200 (pathway in cancer), we revealed four high-risk genes (IGF1R, IGF1, RAS, and BCL2) to be MG risk genes and simultaneously showed they contained miRSNPs in their 3′UTR regions." (PMID 25118158, 2014). "Extensive in vitro and in vivo studies have implicated IGF-1R, IGF-1, and IGF-2 signaling in cancer development, progression, and maintenance." (PMID 25424625, 2014). "In vitro studies demonstrate that IGF1 rescues cancer cells from chemotherapy-induced apoptosis, and high expression is associated with a metastatic phenotype." (PMID 25170759, 2014). "Preclinical studies have identified local IGF-1 synthesis in several cancer cell types, including HCC, leading to autocrine and paracrine effects on cell cycle progression and inhibition of apoptosis." (PMID 25052889, 2014). "In order to compare Igf-1 isoform content at the transcript level in cancer cells, qRT-PCR was performed." (PMID 25018100, 2014). "Based on the expression results, we anticipated that the HeLa, U2OS, HepG2, K562 cancer cells would also display a range of IGF-1 protein levels." (PMID 25018100, 2014). "miRNAs that regulate the IGF-1 signaling are prime targets for the development of novel therapies for several disease including cancer." (PMID 25628647, 2014). "On the other hand, in both males and females with a history of cancer, lower IGF-1 levels predicted longer survival (P < 0.01)." (PMID 24618355, 2014). "Insulin and IGF1 are growth factors with putative regulatory roles in proliferation, survival and cancer progression." (PMID 25373319, 2014). "According to the topological properties of MSSPN and detailed mechanism dissection, we revealed the potentially significant roles of hsa05200 (pathway in cancer), four high-risk genes (IGF1R, IGF1, RAS, and BCL2), and associated miRSNPs in MG." (PMID 25118158, 2014).